TPH1 (tryptophan hydroxylase 1)
Diseases named in the same sentence as TPH1 in open-access papers (continued):
Sharing a sentence is not in itself a finding about the gene and the disease.
Anxiety (18 papers, 2008 to 2025). Intense feelings of nervousness, tension, or panic often arise in response to interpersonal stresses. "Anxiety is a common feature of different psychopathologies that have been linked to human TPH1 polymorphisms." (PMID 35563331, 2022). "We observed associations between loci on Sp2 (rs3708840) and Tph1 (rs262731280) and anxiety phenotype measures, which remained significant after multiple testing correction at q = 0.01." (PMID 28145470, 2017). "Two anxiety-related phenotypes measured in the light-dark exploration test showed significant association with a locus on Tph1 (rs262731280; missense mutation predicting tyrosine to cysteine change, Y206C), encoding tryptophan hydroxylase, a rate-limiting enzyme involved in 5HT synthesis." (PMID 28145470, 2017). "Specificity protein 2 (Sp2, rs3708840), tryptophan hydroxylase 1 (Tph1, rs262731280) and serotonin receptor 3A (Htr3a, rs50670893) were associated with activity/anxiety behaviours, and microtubule-associated protein 2 (Map2, rs13475902) was associated with cognitive performance." (PMID 28145470, 2017). "Studies have shown that TPH1 gene polymorphism is also related to the anxiety symptoms in MDD." (PMID 27672527, 2016). "Next, we exposed TPH1+/+ and TPH1−/− rats to the elevated plus maze test to evaluate their anxiety-like behavior, a common feature of a wide range of different psychopathologies linked to TPH1 polymorphisms." (PMID 35563331, 2022). "To evaluate if the change in anxiety is paralleled by changes in brain plasticity in TPH1−/− rats, we measured the levels of Bdnf in the PFC and in the VHip, both at basal level and after one single session of RS." (PMID 35563331, 2022). "It has been shown that anxiety/compulsive behavior and depression-related disorder testing were normal in Tph1 (−/−) mice." (PMID 23516593, 2013). "At a behavioral level, TPH1−/− rats displayed reduced anxiety-like behavior." (PMID 35563331, 2022). "Furthermore, we detected that SPS decreased the expression of TPH1 mRNA in the hippocampus of rat well as anxiety-like behaviors." (PMID 30018659, 2018). "The Wellcome Trust HS resource does not contain measures from the light dark exploration test, and none of the regions reported to associate with elevated plus maze performance (also indexing anxiety) in Northport Stock were on chromosome 7, where Tph1 is located." (PMID 28145470, 2017). "Nevertheless, the effects of TTC9A−/− on estrogen regulation of TPH1, TPH2 and 5-HTT which influences anxiety-like behaviors will remain an interesting topic for future investigation." (PMID 27869229, 2016). "While it is unknown if the CNS abnormalities in null and heterozygous embryos from Tph1 (−/−) mothers continue into adulthood, there are studies indicating that altered 5-HT signaling, especially during early postnatal development, can lead to other disorders such as anxiety in the adult." (PMID 23516593, 2013). "Our study suggests that the lack of peripheral serotonin in TPH1−/− rats has a positive impact on anxiety-like behavior at basal level." (PMID 35563331, 2022). "Hence, here we analyzed the anxiety levels of TPH1+/+ and TPH1−/− rats by exposing the animals to the elevated plus maze test." (PMID 35563331, 2022). "The Tph1 region did not harbour any anxiety-related QTLs, and there were no cognition-related phenotypes available for the Northport Stock, precluding validation of our Map2 results in an independent dataset." (PMID 28145470, 2017). "Previous results show that Tph1 (−/−) mice on the C57BL/6 background have no abnormalities in anxiety-related behaviors tested in either the elevated plus maze or hold board task." (PMID 23516593, 2013). "It is possible that abnormality of this form of behavior, rather than altered anxiety, accounts for the increased marble burying in TPH2 and TPH1/TPH2 DKO mice." (PMID 18923670, 2008).
irritable bowel syndrome (18 papers, 2016 to 2024). Irritable bowel syndrome (IBS) is a chronic functional condition of the lower gastrointestinal (GI) tract characterized by abdominal pain or discomfort and disordered bowel habit (diarrhea, constipation, or fluctuation between the two). "Decreased 5-HIAA levels associated with the use of a TPH1 inhibitor were reported to correlate with the improvement of irritable bowel syndrome symptoms." (PMID 33466782, 2021). "Lexicon's peripheral serotonin synthesis inhibitors LX1031 and telotristat ethyl (both acting on tryptophan hydroxylase 1 encoded for by the TPH1 gene) showed efficacy in subjects with irritable bowel syndrome and carcinoid syndrome, respectively." (PMID 31064765, 2019). "Significant associations of tryptophan hydroxylase 1 gene polymorphisms, which may modify levels of circulating serotonin, are observed with irritable bowel syndrome-related cognitions in female patients." (PMID 26805875, 2016). "Recent studies established that inhibition of gut-derived Tph1 with the administration of LP533401 effectively protected against irritable bowel syndrome and osteoporosis without affecting brain 5-HT content." (PMID 32477107, 2020). "Only the group of patients with diarrhea-predominant irritable bowel syndrome showed a significant correlation between the TPH1 rs211105 T/T genotype and lower scores for role physical and mental health, and higher scores for indigestion and diarrhea." (PMID 29892168, 2018). "Alterations in mucosal 5-HT levels linked to variations in the expression of Tph-1 and SERT genes, or in the expression of 5-HT intestinal receptors genes 5-HT3 and the 5-HT4, has been reported in intestinal biopsies of patients with Irritable Bowel Syndrome (IBS)." (PMID 34946150, 2021). "On the other hand, irritable bowel syndrome (IBS) with constipation and IBS with diarrhea are characterized by a reduced or increased Tph1 pathway, respectively, and, accordingly, 5-HT4 receptor agonists or 5-HT3 receptor antagonists are suggested as therapy." (PMID 32823705, 2020).
schizophrenia (17 papers, 2007 to 2025). A major psychotic disorder characterized by abnormalities in the perception or expression of reality. "Polymorphisms in TPH1 have been associated with different neurologic disorders, including schizophrenia and suicidal behavior." (PMID 34573388, 2021). "Polymorphism in TPH1 is associated with increased risk for various psychiatric disorders including schizophrenia and bipolar disorder and varies with neurodevelopment with peaks at PND 21 before decreasing in adulthood." (PMID 23447498, 2013). "Genetic variation of TPH1 gene has been associated with the risk of schizophrenia in two recently published studies." (PMID 17521439, 2007). "Other research has reported that TPH1 is associated with schizophrenia." (PMID 36037970, 2022). "Conversion of tryptophan to serotonin may be impaired in the pathogenesis of schizophrenia, as certain TPH1 polymorphisms increase susceptibility to schizophrenia and suicidality." (PMID 33804088, 2021). "We could therefore hypothesize that the previously reported association between TPH1 rs1799913 and schizophrenia may be mediated by serotonergic mechanisms and altered serotonin turnover rate in CNS." (PMID 25073638, 2014). "The TPH1 A779C A-genotype has been associated with lowered serotonin metabolite 5-HIAA levels in the CSF, and on the other hand the functions of TPH1 are related to stress response, which may be associated with susceptibility to schizophrenia." (PMID 17521439, 2007). "The importance of TPH1 comes through possible biological susceptibility through abnormal serotonin levels during the development of brain, or through abnormal response to stress, which may further indicate mental disorders of several types, and particularly schizophrenia." (PMID 17521439, 2007). "Gene TPH1 is identified as important for both bipolar disorder and schizophrenia." (PMID 31530853, 2019). "So far there have been no pharmacogenetic studies of tryptophan hydroxylase 1 (TPH1) gene polymorphism in schizophrenia." (PMID 17521439, 2007). "Another study hypothesized that HTR2A T102C polymorphism, tryptophan hydroxylase 1 (TPH1) gene polymorphism and the G-protein beta-3 subunit (GNB3) C825T polymorphism alter serotonergic neurotransmission and are related to treatment response in schizophrenia." (PMID 36313375, 2022).
breast cancer (15 papers, 2009 to 2025). A primary or metastatic malignant neoplasm involving the breast. "Analysis of 288 breast tumors revealed increased expression of TPH1 in tumors compared to normal breast samples, and an association between increased TPH1 levels and breast cancer progression." (PMID 28404880, 2017). "To gain insight into the possible association between altered 5-HT synthesis and breast cancer progression in actual human tumors, we analyzed TPH1 in histological specimens." (PMID 19903352, 2009). "TPH1 catalyzed the reaction of enhanced degradation of tryptophan to serotonin, and its oncogenetic has been discovered in breast cancer, bladder cell carcinoma, and colon cancer." (PMID 35783506, 2022). "During tumor progression, breast cancer tissues display elevated TPH-1 expression corresponding to enhanced serotonin synthesis." (PMID 35473609, 2022). "Taken together, these studies provide complementary genetic evidence for the role of 5-HTRs and TPH1 in breast cancer and other human cancers." (PMID 34073226, 2021). "Like SERT, TPH1 was also expressed in the majority of the tumor cells in the 3 mouse mammary tumor sections we examined." (PMID 27447971, 2016). "TNBC cell lines (MDA-MB-231, HCC-1395, and Hs578T) expressed higher levels of tryptophan hydroxylase 1 (TPH1) than hormone-responsive breast cancer cell lines (MCF-7 and T47D)." (PMID 27871326, 2016). "We found that mouse mammary tumors arising in the MMTV-Neu N202 transgenic strain express TPH1, 5-HT and SERT in a high fraction of the cells comprising these tumors." (PMID 27447971, 2016). "To identify the cellular source of 5-HT in mouse mammary tumors we stained the same tumor sections with an antibody to TPH1, the rate-limiting enzyme required for 5-HT biosynthesis from tryptophan in non-neuronal tissues." (PMID 27447971, 2016). "Immunohistochemistry analysis of breast cancer tissue using anti-TPH1 antibodies indicated that aberrant expression of TPH1 is associated with the progression of breast cancer." (PMID 27144435, 2016). "It would be premature to suggest that studies reported here are sufficient to establish the prognostic or therapeutic value of the breast cancer TPH1/5-HT system." (PMID 19903352, 2009). "Correspondingly, all of the tissue microarray specimens were harvested from the primary tumor sites of cancers at different stages, but the breast cancer cell lines, which expressed elevated TPH1, were all established from metastasized cells." (PMID 19903352, 2009). "An early finding that piqued our interest in the 5-HT system in human breast cancer was the observation that representative breast cancer cell lines showed significantly elevated TPH1 transcript and protein levels." (PMID 19903352, 2009). "In keeping with the finding that serotonergic antagonists affect the activity of BTIC in mouse and human models of breast cancer, several studies have demonstrated that genetic inhibition of TPH1 or 5-HTRs have a wide range of consequences on tumor cell phenotypes." (PMID 34073226, 2021). "Hence, mammary tumor sections from multiple tumors were stained with antibodies specific for TPH1 and 5-HT using the IF assay format." (PMID 34073226, 2021). "The occurrence of TPH1 in the mammary tumor cells prompted us to learn whether the enzyme was functionally required for sphere formation." (PMID 27447971, 2016). "Since TPH1 is rate limiting for 5-HT synthesis in mammary epithelial cells, as in other systems, breast cancer cells synthesize excess 5-HT, which they may use to support their growth advantages." (PMID 19903352, 2009). "The shift of TPH1 gene expression from the normal tightly-regulated in vivo pattern to a state of homogeneous overexpression in breast cancer cells was reminiscent of the general up-regulation of ER in estrogen-sensitive breast cancer cells." (PMID 19903352, 2009).
breast cancer (continued). "Toward this end, we analyzed TPH1 mRNA levels by reverse-transcriptase-couple polymerase chain reaction (RT-PCR) in different human breast cancer cells (MCF7, MDA-MB-231 and T47D), and compared them to that of non-transformed human mammary epithelial cells (MCF10A)." (PMID 19903352, 2009). "In these cells, 5-HT is essential to enhance the expression of TPH1 (tryptophan hydroxylase 1) and VEGF, supporting the mitogenic and oncogenic impact of 5-HT on breast cancer." (PMID 36650218, 2023). "Although serotonin is mainly known as a neurotransmitter, it is also synthesized by epithelial cells in the mammary gland by tryptophan hydroxylase 1 (TPH1) and plays a role in regulating epithelial homeostasis in breast cancers." (PMID 37046602, 2023). "Treatment with SSRI and TPH1 inhibitors has been reported to suppress the growth of breast tumor-initiating cells (BTIC), and synergizes with chemotherapy, inhibiting breast cancer xenograft growth in mice." (PMID 33859748, 2021). "The operation of TPH1-5-HT-5-HT7 axis utilized PI3K/Akt and JAK2/STAT3 signaling pathways that were activated through Gβγ components of the receptor, consistent with our previous findings in breast cancer cells." (PMID 34771469, 2021). "When the breast cancer cases were sorted according to invasion and progression criteria, TPH1 staining showed a set of nonlinear relationships." (PMID 19903352, 2009). "In short, antagonists of tryptophan hydroxylase 1 (TPH1), monoamine oxidase A (MAO-A), SERT and each of 5 of the 17 5-HTRs inhibited tumorsphere formation by each of six human breast tumor cell lines independent of the breast cancer subtype that they model." (PMID 32758183, 2020).
carcinoid syndrome (12 papers, 2009 to 2025). "ASCL1 may have a coordinating role in production of serotonin by transcriptional regulation of TPH1 and could thereby be involved in causing the carcinoid syndrome in patients with PET." (PMID 19744316, 2009). "In conclusion, the Tph1 inhibitor TE is currently used in clinical practice to treat carcinoid syndrome." (PMID 40937192, 2025). "For example, para-chlorophenylalanine (pCPA), also known as fenclonine, is a classic TPH1 inhibitor that has been developed to treat carcinoid syndrome." (PMID 35684355, 2022). "For pNET patients with carcinoid syndrome (less than 1%), telotristat ethyl is an oral tryptophan hydroxylase 1 (TPH1) inhibitor that can provide relief from symptoms, particularly by decreasing the number of daily bowel movements." (PMID 34680266, 2021). "Mouse mutant phenotypes for Slc6a4 [selective serotonin reuptake inhibitor (SSRI) drug target] and Tph1 (carcinoid syndrome drug target) have been examined by independent laboratories, but not by the IMPC." (PMID 31064765, 2019). "Recently, telotristat ethyl was marketed as a TPH1 inhibitor for carcinoid syndrome." (PMID 35684355, 2022). "More recent molecules such as Telotristat etiprate, which more potently inhibits TPH1/2 than pCPA, with better selectivity over related aromatic amino acid hydroxylases, have demonstrated efficacy in carcinoid syndrome trials showing some symptomatic improvements and good tolerability." (PMID 28529483, 2017). "Telotristat ethyl (TE), which is an oral inhibitor of Tph1, has been approved by the United States Food and Drug Administration (US FDA) to relieve diarrhea symptoms in patients with carcinoid syndrome." (PMID 40937192, 2025). "TPH1 inhibitors, such as telotristat ethyl (TE), have received FDA approval for treating carcinoid syndrome and exhibit potent inhibition of 5-HT synthesis." (PMID 40666095, 2025). "For example, studying Tph1 knockout mice (lacking peripheral serotonin) aided the development of telotristat ethyl, an approved treatment for carcinoid syndrome." (PMID 31064765, 2019).
osteoporosis (11 papers, 2012 to 2025). A condition of reduced bone mass, with decreased cortical thickness and a decrease in the number and size of the trabeculae of cancellous bone (but normal chemical composition), resulting in increased fracture incidence. "Cytokines and chemokines such as TNF-α, CCL-2, IL-10, SERT (Serotonin Transporter) and Tph1 may be possible mediators between the GM and steroid deficiency-induced osteoporosis." (PMID 32484785, 2020). "Tryptophan hydroxylase 1 (Tph-1) is the main enzyme in the biosynthesis of peripheral blood albumin, providing a new target for the design of anabolic agents for osteoporosis." (PMID 37959859, 2023). "Yadav and co-workers reported that a small molecule inhibitor of TPH1 has the potential to become a new class of bone anabolic drugs that can be added to the armamentarium to treat osteoporosis." (PMID 23665899, 2013). "The theoretical results can offer some useful references for the design of new TPH1 inhibitors as anti-osteoporosis drugs." (PMID 22754301, 2012). "Small molecule inhibitors of TPH1 can be considered as a new target to treat osteoporosis and this mechanism is different from any known drugs (Estrogen or Bisphosphonates)." (PMID 22754301, 2012). "Thus, TPH1 can be considered as a new drug target and this mechanism is totally different from any known anti-osteoporosis drugs." (PMID 23665899, 2013). "Therefore, structure-activity relationship (SAR) studies on the known TPH1 inhibitors are very interesting and meaningful for discovering new anti-osteoporosis candidate compounds." (PMID 22754301, 2012). "Inhibition of tryptophan hydroxylase-1 (TPH-1), the rate-limiting enzyme in biosynthesis of circulating serotonin, leads to increased bone formation in ovariectomized rodents with osteoporosis." (PMID 25279460, 2014).
bipolar disorder (8 papers, 2005 to 2021). A disorder of the brain that causes unusual shifts in mood, energy, activity levels and the ability to carry out day-to-day tasks. "It was also shown that one of the known SNPs in the TPH1 gene (rs1800532) is a potential biomarker for bipolar disorder and alcohol-dependence risk in the Caucasian population." (PMID 34772352, 2021). "They found that the A/A genotype of TPH1 A218C polymorphism was associated with the risk of bipolar disorder in the Caucasian population." (PMID 28951738, 2017).